ADIPOQ (adiponectin, C1Q and collagen domain containing)
Diseases named in the same sentence as ADIPOQ in open-access papers (continued):
Sharing a sentence is not in itself a finding about the gene and the disease.
breast tumor (5 papers, 2020 to 2025). "Multivariable-adjusted associations of body fatness measures with ADIPOQ protein and ADIPOQ gene expression in breast tumor tissues." (PMID 35846306, 2022). "We obtained during surgery fresh breast tumour tissue and a fragment of breast adipose tissue adjacent to the tumour and analyzed the levels of adiponectin (ADIPOQ) and its receptor ADIPOR1 by Western blot." (PMID 41456223, 2025). "ADIPOR2 is a receptor for adiponectin C1Q and collagen domain containing (ADIPOQ), an adipocytokine secreted by adipocytes in the breast tumor microenvironment, which negatively regulates cancer cell growth." (PMID 35739271, 2022). "Subgroup analysis of the multivariate associations of LEP, LEPR, ADIPOQ, ADIPOR1, and ADIPOR2 IHC expression with breast tumor clinicopathologic features among Black women yielded similar findings." (PMID 32046756, 2020). "So, lower IHC expression of ADIPOQ might be consistent with breast tumors progressing towards increasing aggressiveness (but only in some instances)." (PMID 32046756, 2020). "Most previous studies by other groups and our own that analyzed ADIPOQ and/or ADIPOR1 levels were performed on paraffin-embedded breast tumor tissue using immunohistochemistry." (PMID 41456223, 2025). "Building on our prior research, here we examined the associations of body fatness measures with protein and gene expression of the adipokines, LEP and ADIPOQ, and the adipokine receptors, LEPR, ADIPOR1, and ADIPOR2 in breast tumor tissues." (PMID 35846306, 2022). "We did not observe any differences in ADIPOQ protein levels in breast tumour tissue or adjacent breast adipose tissue." (PMID 41456223, 2025). "Variation in LEPR IHC expression was observed by breast tumor clinicopathologic features, while the expression of LEP, ADIPOQ, ADIPOR1, and ADIPOR2 did not appear to vary by tumor clinicopathology." (PMID 32046756, 2020).
colon carcinoma (5 papers, 2011 to 2023). "The rs12733285C/T genotype and the A allele of rs1342387 (A/G or A/A) of ADIPOR1 are protective factors for CRC, while the rs266729G/C genotype and the G allele of ADIPOQ are risk factors for colon cancer." (PMID 33167521, 2020). "The anticancer role of ADIPOQ was mainly induced by its receptors, which have been demonstrated to repress colon cancer cell lines (including HCT116, HT29 and LoVo) proliferation via ADIPOR1- and -R2-mediated 5′-AMP -activated protein kinase (AMPK)." (PMID 22087284, 2011). "This case-control study demonstrates that polymorphisms in ADIPOR1 (rs12733285, rs1342387) are associated with the decreased risk of CRC, and polymorphism in ADIPOQ (rs266729) is a risk for colon cancer but not for rectal cancer." (PMID 21749709, 2011). "Previously studies have documented that ADIPOQ repressed colon cancer cell lines (including HCT116, HT29 and LoVo) proliferation via ADIPOR1- and -R2-mediated AMPK, whereas, knockdown of ADIPORs such as ADIPOR1 relieved the suppressive effect of ADIPOQ on the growth of cancer cells." (PMID 22087284, 2011). "Furthermore, knockdown of ADIPORs could relieve the suppressive effect of ADIPOQ on the growth of colon cancer cells." (PMID 22087284, 2011).
diabetic nephropathy (5 papers, 2009 to 2026). "In this meta-analysis, variants within or near VEGFA (two variants), CCR5 (two variants), CCL2, IL-1, MMP9, EPO, IL-8, ADIPOQ and IL-10 were significantly associated with diabetic nephropathy." (PMID 25280384, 2014). "However, there are relatively few studies on the relationship between ADIPOQ gene polymorphisms and the occurrence and severity of diabetic kidney disease (DKD)." (PMID 41824816, 2026). "MCF2L2, ADIPOQ and SOX2 genes are located in chromosome 3q26-27, which is linked to diabetic nephropathy (DN)." (PMID 20667095, 2010).
end-stage renal disease (5 papers, 2012 to 2024). "ADIPOQ is associated with chronic kidney failure, end-stage renal disease, and renal hypertrophy." (PMID 30547763, 2018).
dementia (4 papers, 2020 to 2025). Loss of intellectual abilities interfering with an individual's social and occupational functions. "Although the expression ADIPOQ has been mainly observed in fat tissue, genetic variants of ADIPOQ showed association with diverse disease traits, such as heart failure and dementia." (PMID 36114174, 2022). "Moreover, increased AdipoQ levels were revealed in the cerebrospinal fluid (CSF) and plasma of individuals with MCI as well as sporadic AD, while plasma concentrations of AdipoQ was positively associated with dementia." (PMID 33584324, 2020). "Since most of the identified proteins are not present in both diseases, we performed two independent PPI analyses: the first using the proteins associated with HF (NPPB, REN, ADIPOQ, VWF, ACE, IL6, and CRP) and the second using the proteins involved in dementia (CRP, APP, MAPT, APOE, ACE, and IL6)." (PMID 40699836, 2025). "AdipoQ also co-localized with Lewy bodies in the brain of dementia patients." (PMID 33584324, 2020). "Several reports have shown that the relationship between dementia and AdipoQ levels might be sex-dependent." (PMID 33584324, 2020). "Examination of the highlighted keywords revealed the commonality between HF and dementia, namely IL6, ACE, APOE, APP, ADIPOQ, LEP, and NPPB, suggesting that these proteins may link the two pathologies." (PMID 40699836, 2025).
endothelial dysfunction (4 papers, 2022 to 2025). In vascular diseases, endothelial dysfunction is a systemic pathological state of the endothelium (the inner lining of blood vessels) and can be broadly defined as an imbalance between vasodilating and vasoconstricting substances produced by (or acting on) the endothelium. "Remarkably, ADIPOQ consistently showed downregulation in STEMI patients across both the acute and stabilization phases compared to TS, suggesting its potential as a diagnostic marker and underscoring its involvement in systemic inflammation and endothelial dysfunction." (PMID 39513871, 2024).
hyperlipidemia (4 papers, 2012 to 2026). "After exploring the PPI network of DO for hyperlipidemia, the key targets of DO for hyperlipidemia included AKT1, TNF, PPARG, ADIPOQ, and APOB." (PMID 35502176, 2022). "The network analysis uncovered that naringenin, isorhamnetin, and taxifolin might be the compounds in DO that are mainly in charge of its roles in hyperlipidemia and might play a role by modulating the targets (including PPARG, ADIPOQ, AKT1, TNF, and APOB)." (PMID 35502176, 2022). "In summary, AKT1, TNF, PPARG, ADIPOQ, and APOB may be targets for the action of DO in the treatment of hyperlipidemia." (PMID 35502176, 2022).
psoriasis (4 papers, 2023 to 2025). An autoimmune condition characterized by red, well-delineated plaques with silvery scales that are usually on the extensor surfaces and scalp. "Among these, ADIPOQ has the potential to serve as a diagnostic marker for psoriasis." (PMID 40584617, 2025). "The downregulation of H3K18la is a key factor in decreasing ADIPOQ levels in patients with psoriasis." (PMID 40584617, 2025). "In the skin tissues of psoriasis patients, ADIPOQ levels are significantly reduced, and ADIPOQ possesses the potential for diagnosing psoriasis." (PMID 39278916, 2024). "On the other hand, the ADIPOQ and LEP genes were found to play a notable role in the gene-to-gene interaction networks in the genomes of psoriasis patients." (PMID 36980866, 2023).
thyroid cancer (4 papers, 2020 to 2024). "In vitro functional experiments confirmed that AdipoQ reconstituted from adipose stem cells could significantly inhibit the proliferation and migration of thyroid cancer cells, and that AdipoQ can inhibit the growth and proliferation of thyroid cancer cells by activating AMPK." (PMID 39349421, 2024).
heart failure (3 papers, 2022 to 2025). Inability of the heart to pump blood at an adequate rate to meet tissue metabolic requirements. "During the progression of heart failure, ADIPOQ levels increase with disease severity, with elevated levels being associated with poor prognosis." (PMID 40908499, 2025).
hypoadiponectinemia (3 papers, 2021 to 2025). "That the -11377C/G (rs266729) gene variant of the ADIPOQ gene was associated with T2DM in the population of Jammu and Kashmir and both were associated with hypoadiponectinemia were also investigated." (PMID 41341358, 2025). "Mutations in the ADIPOQ gene are doing the multimerization process of proteins that can affect the activity of proteins biologically by disturbing the assembling of trimeric and high-molecular-weight (multimeric) forms of proteins that may lead to hypoadiponectinemia." (PMID 41341358, 2025).
liver fibrosis (3 papers, 2021 to 2025). "In the same study, it was shown that the loss of AdipoQ expression specifically in murine HSCs also demonstrated significantly worsened liver fibrosis." (PMID 40985048, 2025).
preeclampsia (3 papers, 2018 to 2026). Preeclampsia is a hypertensive disorder of pregnancy that is characterized by new-onset hypertension with proteinuria presenting after 20 weeks of gestation, and depending on mild or severe forms may initially present with severe headache, visual disturbances, and hyperreflexia. "ADIPOQ gene has polymorphisms that modulate adiponectin levels and are linked to several diseases, including gestational hypertension (GH) and preeclampsia (PE)." (PMID 41602445, 2026).
sarcopenia (3 papers, 2023 to 2025). Progressive decline in muscle mass due to aging which results in decreased functional capacity of muscles. "Bioinformatics analysis identified 78 biphenotypic target genes shared by LT and sarcopenia, with hub genes including IL1B, ADIPOQ, and TNF showing strong associations." (PMID 41211064, 2025). "In contrast, newer myokines/adipokines FNDC5, METRNL, RETN, and NAMPT, together with AdipoQ in sarcopenia, were uniformly negatively correlated, suggesting a counter-regulatory or compensatory circuit activated by mitochondrial stress." (PMID 40869253, 2025). "Middle-aged and elderly individuals with lower skeletal muscle function and BMD had higher expression levels of LEP, ADIPOQ, RBP4, DPP4 and inflammatory markers, suggesting that adipokines may play a role in the activation of inflammation and lead to the development of sarcopenia and osteoporosis." (PMID 37525169, 2023).
aneurysm (2 papers, 2019 to 2025). Bulging or ballooning in an area of an artery secondary to arterial wall weakening. "By affecting these pathways, ADIPOQ could play a crucial role in the progression or stabilization of aneurysms." (PMID 40313967, 2025). "Moreover, Adiponectin (ADIPOQ) seems relevant, as ADIPOQ is elevated in Kawasaki patients (aneurysms in coronary artery)." (PMID 31683995, 2019). "In our study, we performed a gene set enrichment analysis (GSEA) to investigate the roles of ADIPOQ and IL21R in aneurysm pathophysiology, focusing on their involvement in immune-related pathways." (PMID 40313967, 2025). "These analyses collectively highlight ADIPOQ and IL12-R as critical genes in aneurysm pathology and potential targets for further investigation and therapeutic intervention." (PMID 40313967, 2025).
chronic kidney failure (2 papers, 2014 to 2018). "Disease pathway analysis showed IL6, EPO, ADIPOQ and CCR2 to be involved in chronic kidney failure." (PMID 25280384, 2014).
cognitive decline (2 papers, 2020 to 2022). "An intracerebroventricular dose of AdipoQ recovered cognitive decline and reduced glycogen synthase kinase 3β (GSK3β)-induced tau hyperphosphorylation in AD-related areas in a rat paradigm of streptozotocin-mediated brain pathology." (PMID 33584324, 2020). "The outcome of a cohort study performed by the Mayo Clinic Study of Aging indicated that elevated levels of plasma AdipoQ were interrelated with imaging data for cortical and hippocampal volumes, cognitive declines, and positron emission tomography." (PMID 33584324, 2020). "Therefore, the obtained results advocate that higher AdipoQ predicts cognitive decline and neurodegeneration in aging." (PMID 33584324, 2020). "Furthermore, a clinical trial reported that patients with elevated AdipoQ concentrations exert better performances in a prolonged word memory test, advocating the idea that AdipoQ is a protective factor against cognitive failure suggesting a novel therapeutic approach in cognitive decline." (PMID 33584324, 2020). "Furthermore, based on the AdipoQ levels, one is not able to foresee the development of cognitive decline from normal conditions to MCI and from MCI to AD, respectively." (PMID 33584324, 2020).
Cognitive impairment (2 papers, 2020 to 2021). Abnormal cognition is characterized by deficits in thinking, reasoning, or remembering. "Dysregulation of AdipoQ signaling may disrupt brain homeostasis and increase the risk of cognitive impairment." (PMID 33584324, 2020).
joint diseases (2 papers, 2015 to 2018). "ADIPOQ has been suggested to be pro-inflammatory in joint diseases, but in our study, we find lower ADIPOQ mRNA levels in patients than in healthy controls, arguing against a pro-inflammatory function in AT." (PMID 25996876, 2015). "It was previously shown that adipose tissue plays an important role in inflammation and that ADIPOQ might have pro-inflammatory properties in joint diseases." (PMID 29385715, 2018). "Thus, ADIPOQ might have pro-inflammatory functions in joint diseases." (PMID 25996876, 2015).
keloid (2 papers, 2021 to 2022). An irregularly shaped, elevated mark on the skin caused by deposits of excessive amounts of collagen during wound healing. "The expression of FoxO1 is highly increased in fibroblasts and inflammatory cells in keloid scars and the gene expression levels of several wound growth factors, including FGF2, Notch1, and ADIPOQ, are also decreased in keloid scars." (PMID 34418600, 2021).
knee osteoarthritis (2 papers, 2019). "In a word, ADIPOQ gene mutation may be associated with an increased risk of knee osteoarthritis." (PMID 31139654, 2019). "Different from microarray analysis results, ADIPOQ was significantly increased in knee osteoarthritis synovial membranes in our study." (PMID 31139654, 2019). "The statistical result of the verification experiment showed that the expression level of ADIPOQ, IL6, and CXCR1 was significantly increased in knee osteoarthritis synovial membranes (p < 0.05)." (PMID 31139654, 2019).
lipodystrophy (2 papers, 2019 to 2022). A congenital or acquired disorder characterized by abnormal loss or redistribution of the adipose tissue in the body. "Adipocyte-specific seipin deletion, either under the aP2 promoter or the AdipoQ promoter, leads to progressive lipodystrophy." (PMID 35250856, 2022).
liver cancer (2 papers, 2020 to 2021). An epithelial or non-epithelial malignant neoplasm that arises from the liver. "ADIPOQ in NAFLD patients is a risk factor for progression to liver cancer, and ADIPOQ is significantly decreased in patients with liver metastases." (PMID 34988225, 2021). "Through dose-response, we can more clearly explore the relationship between AdipoQ and leptin and liver cancer risk." (PMID 33256658, 2020). "Animal studies also proven that AdipoQ has a protective effect in liver cancer and cirrhosis, and high AdipoQ levels in patients with cirrhosis and HCC are related to disease progression." (PMID 33256658, 2020).
osteoporosis (2 papers, 2021 to 2023). A condition of reduced bone mass, with decreased cortical thickness and a decrease in the number and size of the trabeculae of cancellous bone (but normal chemical composition), resulting in increased fracture incidence. "Through the study of ADIPOQ gene loci and osteoporosis risk, the ADIPOQ gene has been proven to be a potential useful genetic marker for predicting the risk of osteoporosis in middle-aged and elderly Mulam people." (PMID 34948648, 2021). "The exact molecular mechanism of ADIPOQ gene polymorphism and osteoporosis remains unclear and could be profitable in future studies." (PMID 34948648, 2021). "This study found that GC genotypes at the rs266729 locus of ADIPOQ gene, GA and GG genotype at rs710445 locus, and haploid CCGAA and GGTAG were correlated with osteoporosis." (PMID 34948648, 2021).
prediabetes (2 papers, 2018 to 2024). "Our findings indicate that serum adiponectin and SNPs in the ADIPOQ gene are associated with prediabetes in Jordan." (PMID 30360393, 2018). "The rs1501299 SNP of the ADIPOQ gene was associated with prediabetes in our population (p = 0.041)." (PMID 30360393, 2018). "We next wanted to determine if ADIPOQ gene variants were associated with prediabetes." (PMID 30360393, 2018). "In addition to our finding that the rs1501299 SNP of ADIPOQ was associated with prediabetes in Jordan, we previously reported that rs1501299 was also associated with PCOS in Jordanian women." (PMID 30360393, 2018). "Adiponectin (ADIPOQ) was associated with T2D but was not changed in the prediabetes population." (PMID 39589852, 2024).
rheumatoid arthritis (2 papers, 2017 to 2019). A chronic, systemic autoimmune disorder characterized by inflammation in the synovial membranes and articular surfaces. "ADIPOQ level is associated with radiographic changes and progression of rheumatoid arthritis, and with cartilage destruction in OA patients." (PMID 30777928, 2019).
systemic lupus erythematosus (2 papers, 2017 to 2025). An autoimmune multi-organ disease typically associated with vasculopathy and autoantibody production. "In addition, several autoimmunity-related proteins are linked to coagulation (e.g., AGT, F2) and to specific ADs, such as systemic lupus erythematosus (e.g., AGT, C1S, C7, MMP2, VWF) or autoimmune rheumatic diseases (e.g., ADIPOQ, AGT, MASP1, MMP2)." (PMID 40546301, 2025).
triple-negative breast carcinoma (2 papers, 2022 to 2025). An invasive breast carcinoma which is negative for expression of estrogen receptor (ER), progesterone receptor (PR), and human epidermal growth factor receptor 2 (HER2). "The results of this study highlight the potential role of epigenetic regulation of ADIPOQ, GAS5, GATA4, and YAP1 in the molecular pathology of triple-negative breast cancer." (PMID 41226688, 2025). "Analysis of gene expression using bc-GenExMiner showed that the mRNA levels of FABP, ADIPOQ, PPARG, CD36, PPARGC1A, and CREBBP were significantly lower in basal-like and triple-negative breast cancer (TNBC) cells than in non-basal-like and non-TNBC cells." (PMID 36114448, 2022).
acne (1 paper, 2020). An inflammatory process of the sebaceous glands which is characterized by comedones, nodules, papules and/or pustules on the skin. "Current findings showed that rs1501299 of the ADIPOQ gene might be associated with changes in HDL level in acne patients following treatment with isotretinoin." (PMID 32411191, 2020).
alopecia (1 paper, 2021). Hair loss usually from the scalp. "Mice born from mothers lacking or overexpressing adiponectin (AdipoQ-KO or AdipoQ-Tg, respectively) display growth retardation, alopecia and skin inflammation." (PMID 33751362, 2021).
aneurysmal disease (1 paper, 2019). "In this AAA gene list we identified previously AAA-associated genes COL11A1, ADIPOQ, and LPL, thus validating our approach as well as novel genes; CXCL13, SLC7A5, FDC-SP not previously linked to aneurysmal disease." (PMID 31683995, 2019).
atopic dermatitis (1 paper, 2021). "Low plasma ADIPOQ levels have been associated with an increase in the manifestation of atopic dermatitis in mice." (PMID 34438765, 2021).